PDIA3 (protein disulfide isomerase family A member 3)
Diseases named in the same sentence as PDIA3 in open-access papers (continued):
Sharing a sentence is not in itself a finding about the gene and the disease.
colorectal cancer (continued). "Hence, we postulate that PDIA3 plays an integral role in the pathogenesis and progression of colorectal cancer." (PMID 38761176, 2024). "Thus, it is evident that PDIA3 stimulates the proliferative capacity of colorectal cancer cells by masterminding the STAT3/PD-1 signaling paradigm, in tandem with refining macrophage M2 polarization and the secretion of tissue-specific proteases." (PMID 38761176, 2024). "Cellular experimentation underpinned the proposition that PDIA3 impels the M2 polarization of tumor-aligned macrophages, alongside fostering proliferation and the potential for metastasis in colorectal cancer, all by the delicate modulation of the STAT3/PD-1 signaling continuum." (PMID 38761176, 2024). "Investigations into the role of PDIA3 in colorectal cancer progression revealed its significant influence on disease development, evidenced by a xenograft model in nude mice showing a reduction in tumor growth with PDIA3 suppression." (PMID 38761176, 2024). "Moreover, PDIA3 was demonstrated to catalyze colorectal cancer cell motility by governing the STAT3/PD-1 pathway, while simultaneously modulating M2 macrophage polarization and protease secretion." (PMID 38761176, 2024). "Additionally, immunohistochemical and molecular techniques substantiated the elevated levels of PDIA3 in colorectal carcinoma tissue compared to normal colon tissue, highlighting the prevalence of this protein in carcinogenic samples." (PMID 38761176, 2024). "Results disclosed that colorectal carcinomas exhibited significantly increased PDIA3 expression." (PMID 38761176, 2024). "Value of HP and PDIA3 levels to assessment of colorectal cancer patients." (PMID 35860021, 2022). "Value of HP and PDIA3 levels to assessment of colorectal cancer patients at progressive stage." (PMID 35860021, 2022). "Value of HP and PDIA3 levels to assessment of patients with early colorectal cancer." (PMID 35860021, 2022). "There were also significant differences in HP and PDIA3 levels between colorectal cancer patients at an early stage and those at the progressive stage, indicating that HP and PDIA3 expressions were high in malignant tumors and would continuously increase alongside disease progression." (PMID 35860021, 2022). "However, the presence of autoantibodies to PDIA3 antigen favors the development of an efficient and specific T-cell response against PDIA3 in patients with colorectal cancer, indicating that they have antitumor effector functions." (PMID 29228584, 2017). "These revelations intimate that PDIA3 may contribute to the enhanced proliferation of colorectal cancer cells through its masterful orchestration of the STAT3/PD-1 signaling axis, thereby engendering an enriched environment for M2 macrophage polarization and protease secretion." (PMID 38761176, 2024). "Acknowledging PDIA3’s heightened expression in neoplastic conditions, we explored whether these observations are echoed in the genetically modified nude mouse model’s response to colorectal cancer." (PMID 38761176, 2024). "Precise elucidation of the mechanisms by which PDIA3, alongside STAT3 and the PD-1/PD-L1 axis, influences therapeutic denouements in colorectal cancer remains quintessential." (PMID 38761176, 2024).
endometrial cancer (9 papers, 2016 to 2024). Primary or metastatic malignant neoplasm involving the endometrium (mucous membrane that lines the endometrial cavity). "Through our analysis, we observed the overexpression of PDIA3 in endometrial cancer tissues, along with its association with tumor grade, prognosis, and other factors." (PMID 37909009, 2023). "Furthermore, we examined the association between PDIA3 protein expression and clinical-pathological parameters of endometrial cancer." (PMID 37909009, 2023). "Our research involved introducing PDIA3 as a novel biomarker for endometrial cancer and validating its expression using public datasets and primary tumor tissues." (PMID 37909009, 2023). "The relationship between PDIA3 and the infiltration levels of six immune cell types in endometrial cancer under different SCNA states is depicted." (PMID 37909009, 2023). "Based on the expression results obtained from the GSE17025 dataset, it was determined that PDIA3 expression in endometrial cancer (EC) tissues was significantly higher compared to adjacent samples (P = 4.1E-03)." (PMID 37909009, 2023). "In endometrial cancer, the relationship between the expression levels of PDIA3 gene or the levels of immune cell infiltration and patient survival can be visually assessed using Kaplan-Meier survival curves." (PMID 37909009, 2023). "IHC analysis revealed a significant increase in PDIA3 expression in endometrial cancer (EC) tissues compared to adjacent normal tissues (P = 0.01)." (PMID 37909009, 2023). "In this study, we aimed to assess the clinical significance of PDIA3 in endometrial cancer by evaluating its expression in public datasets and primary tumor samples from participating hospitals, with the goal of identifying its potential as a novel biomarker." (PMID 37909009, 2023). "Although the expression of PDIA3 was elevated in endometrial cancer tissues, interestingly, the expression of PDIA3 in EC tissues was inversely correlated with clinicopathological parameters." (PMID 37909009, 2023). "Conducting such research will contribute to a comprehensive understanding of the role of PDIA3 in endometrial cancer and its potential as a therapeutic target." (PMID 37909009, 2023). "In summary, our study aimed to investigate the expression of PDIA3 in endometrial cancer and analyze its correlation with clinical parameters and prognosis." (PMID 37909009, 2023). "This study aims to investigate the potential of PDIA3 as a novel prognostic biomarker and therapeutic target for Endometrial Cancer (EC) with the ultimate goal of improving survival rates in EC patients." (PMID 37909009, 2023). "Further mechanistic investigations are required to establish the involvement of PDIA3 in the pathogenesis of endometrial cancer." (PMID 37909009, 2023). "On the other hand, immunohistochemical analysis of PGR and PDIA3 expression showed significant downregulation of these factors in endometrial cancer compared to normal tissues." (PMID 33292199, 2020). "Expression of PDIA3 between endometrial cancer and normal tissues by IHC." (PMID 37909009, 2023). "Finally, we evaluated the prognostic value of PDIA3 in endometrial cancer." (PMID 37909009, 2023). "Tissue collected from stage IA endometrial cancer showed upregulation of the proteins GRP78, GSTP1, ACTG, PDIA3, and ENOA and downregulation of ALBU compared to BEC samples." (PMID 39194522, 2024). "However, the role of PDIA3 in endometrial cancer remains unknown." (PMID 37909009, 2023).
Alzheimer disease (8 papers, 2012 to 2024). A progressive, neurodegenerative disease characterized by loss of function and death of nerve cells in several areas of the brain leading to loss of cognitive function such as memory and language. "PDIA3 is associated with different human pathologies such as cancer, prion disorders, Alzheimer's disease, and Parkinson's diseases and it has the potential to be a pharmacological target." (PMID 28044092, 2016). "Similar conclusions were reached by researchers who demonstrated an age-dependent increase in PDIA3 levels in the amygdala, entorhinal cortex, and ventral hippocampus of Alzheimer’s disease model mice (3×Tg-AD)." (PMID 39769211, 2024). "A similar neuroprotective role for PDIA3 has been documented against β-amyloid aggregation in Alzheimer's disease." (PMID 22715419, 2012). "Moreover, immunohistochemical analysis revealed a direct correlation between cellular levels of beta-amyloid and PDIA3 across all examined brain regions, suggesting a potential interaction in the pathogenesis of Alzheimer’s disease." (PMID 39769211, 2024). "The role of ERp57/PDIA3 was linked to ER stress pathways, which characterize diseases such as Alzheimer’s disease (AD) and amyotrophic lateral sclerosis (ALS) (in this case, ERp57/PDIA3 also plays a role because of its interaction with the MAM compartment)." (PMID 35109791, 2022).
renal fibrosis (8 papers, 2015 to 2023). A final common manifestation of a wide variety of chronic kidney diseases characterized by glomerulosclerosis and tubulointerstitial fibrosis. "PDIA3 also involved in cytokine-dependent signal transduction, overexpression of it is reported linked to renal fibrosis." (PMID 31139026, 2019). "We characterize one such mediator, PDIA3, as a major contributor to renal fibrosis via its augmentation of TGF-β–driven activation of myofibroblasts." (PMID 36509292, 2022). "In the COL4A3 knockout mouse, an animal model for AS, it has been shown that parallel to the progression of renal fibrosis at different stages of disease, there is a significant increase in ER-stress proteins, including PDIA3." (PMID 33671535, 2021). "In renal fibrosis, PDIA3 has been shown to contribute to extracellular matrix accumulation, which supports our observation of increased PDIA3 expression in injured and fibrotic ATII cells from bleomycin-treated lungs 14 days after injury." (PMID 26035385, 2015). "Importantly, the urinary excretion of PDIA3 in the COL4A3 knockout mice correlates with the progression of renal fibrosis in the first 7 weeks." (PMID 33671535, 2021). "A similar role was described for PDIA3 in remodeling of the ECM during renal fibrosis." (PMID 27240165, 2016).
virus infection (8 papers, 2011 to 2024). "It is important to highlight that PDIA3 is important for antigen presentation during viral infections as reflected in the pathway." (PMID 38025778, 2023). "More recently, a review was published on the role of ERp57/PDIA3 in viral infections, emphasizing that the presence of this protein on the cell surface assists different viruses to enter the cells and replicate." (PMID 35109791, 2022). "Several studies also demonstrated the effects of down-regulation of PDIA3 and PDIA6 individually upon virus infection." (PMID 29404200, 2018). "The change in abundance of eight of the targeted proteins (GPT2, HSPA9, MAPK1, PDIA3, PDIA6, PSMC5, TALDO1, and ATP5B) was predicted to collectively inhibit viral infection (pathway analysis)." (PMID 29404200, 2018). "Eight proteins (GPT2, HSPA9, MAPK1, PDIA3, PDIA6, PSMC5, TALDO1, and ATP5B) were predicted/known to be involved in viral infection." (PMID 29404200, 2018). "Analysis using IPA software suggested that eight of the targeted proteins (ATP5B, GPT2, HSPA9, MAPK1, PDIA3, PDIA6, PSMC5, and TALDO1) were involved in virus infection and their lower protein abundance may inhibit viral infection." (PMID 29404200, 2018).
clear cell renal cell carcinoma (7 papers, 2019 to 2025). "A study on clear cell renal cell carcinoma (ccRCC) highlighted the increased levels of ERp57/PDIA3 and interleukin enhancer-binding factor 3 (ILF3) in ccRCC tissue, which were correlated with poor patient survival." (PMID 35109791, 2022).
Obesity (7 papers, 2019 to 2024). Accumulation of substantial excess body fat. "It was also demonstrated recently that the amount of PDIA3 is reduced in the spermatozoa of male individuals with obesity-associated asthenozoospermia." (PMID 32899471, 2020). "PDIA3 circulating levels were positively associated with obesity markers, IR and LDL-cholesterol." (PMID 38703299, 2024). "Therefore, the results of proteomic analyses indicate that the ER proteins such as RRBP1, CRELD2 and PDIA3 in the exosomes were differentially regulated by the obesity-associated OS condition in the caput epididymis and may indeed affect sperm maturation." (PMID 36411474, 2022). "Previous studies in obesity showed that circulating levels of PDIA3 were increased in pediatric subjects with obesity compared to controls." (PMID 38703299, 2024). "Children with obesity had a higher level of PDIA3 (0.212, 0.187–0.465 ng/ml, p < 0.05) than normal weight patients (0.188, 0.167–0.222 ng/ml), corrected by sex and age." (PMID 36213269, 2022). "Calreticulin (CALR) and PDIA3 circulating levels were assessed on 52 pediatric subjects—26 patients with obesity and 26 normal weight controls (4–18 years)—enrolled in a pilot study." (PMID 36213269, 2022). "This is evidence that PDIA3 could be an early marker of IR, dyslipidemia and other obesity-related complications." (PMID 38703299, 2024). "Thus, in the current study, the differential expression of RRBP1, CRELD2 and PDIA3 in exosomes may indeed attribute to obesity-induced ER stress." (PMID 36411474, 2022). "In addition, given the PDIA3 enrichment in macrophages in tissues of altered stiffness due to obesity and chronic inflammation, changes in potentially mechanosensing self-antigen levels might represent a novel target of study to ameliorate aging and obesity-related conditions." (PMID 39616399, 2024). "PDIA3 was higher (p < 0.02) and CALR slightly higher in children with obesity than in controls." (PMID 36213269, 2022). "Moreover, downregulation of PDIA3 abundance was also reported in two independent proteomics analyses selected for the present systematic review, including samples of SAT and platelets in individuals with obesity compared to lean patients." (PMID 38703299, 2024).
acute myeloid leukemia (6 papers, 2020 to 2025). Acute myeloid leukemia (AML) is a group of neoplasms arising from precursor cells committed to the myeloid cell-line differentiation. "PDIA3 downregulation inhibits the proliferation and invasion of human acute myeloid leukemia cells." (PMID 38213579, 2023). "In acute myeloid leukemia (AML) cells, PDIA3 plays a regulatory role in key cellular processes including apoptosis, proliferation, invasion, and migration." (PMID 40868343, 2025). "Downregulation of PDIA3 inhibits proliferation and promotes apoptosis, making it a novel therapeutic target for colorectal cancer (CRC) and acute myeloid leukemia (AML)." (PMID 35401558, 2022).
amyotrophic lateral sclerosis (6 papers, 2017 to 2024). Amyotrophic lateral sclerosis (ALS) is a neurodegenerative disease characterized by progressive muscular paralysis reflecting degeneration of motor neurons in the primary motor cortex, corticospinal tracts, brainstem and spinal cord. "PDIA3 has been linked to amyotrophic lateral sclerosis, and its deletion is embryonically lethal." (PMID 39275253, 2024). "Specifically, Pr Hetz focused on the significance of PDIA3 in amyotrophic lateral sclerosis (ALS), a progressive paralytic disorder characterized by the selective degeneration of motor neurons in the brainstem and cerebral cortex." (PMID 37409695, 2023). "Another study identified ERp57/PDIA3 as protective against mutant SOD1-induced cellular pathology in amyotrophic lateral sclerosis." (PMID 35109791, 2022). "Association between PDIA3 and the amyotrophic lateral sclerosis may not be surprising as PDIA3 expression is high in the brain during embryonic development." (PMID 28487627, 2017).
ischemia (6 papers, 2017 to 2024). A hypoperfusion of the BLOOD through an organ or tissue caused by a PATHOLOGIC CONSTRICTION or obstruction of its BLOOD VESSELS, or an absence of BLOOD CIRCULATION. "Other studies have seen a beneficial effect in models of ischemia or traumatic brain injury by manipulating another vitamin D receptor, Protein Disulfide Isomerase A3 (PDIA3, Erp57)." (PMID 39275253, 2024). "This study showed that Tat-ERp57/PDIA3 acts as a neuroprotective agent against ischemia by attenuating oxidative damage and blocking the apoptotic pathway related to the UPR." (PMID 35109791, 2022). "In the vehicle‐treated control and Tat‐PDIA3‐treated control groups, spontaneous motor activity was showed similar levels before and after ischemia." (PMID 31957985, 2020). "On day 24 of vehicle or Tat‐PDIA3 treatment, ischemia was transiently induced by occlusion of both common carotid arteries for 5 min." (PMID 31957985, 2020). "Further, Tat-PDIA3 significantly ameliorated the ischemia-induced deficits in motor function, based on Tarlov’s criteria, 24–72 h after ischemia/reperfusion, as well as the degeneration of motor neurons in the ventral horn 72 h after ischemia/reperfusion." (PMID 28981094, 2017). "In the Tat-PDIA3-treated group, GPx activity significantly increased (1.555- and 2.394-fold) 24 h and 72 h after ischemia, compared the vehicle-treated group, although it was lower in comparison to the control group." (PMID 28981094, 2017). "However, we observed that administration of Tat‐PDIA3 ameliorated the ischemia‐induced hyperactivity in gerbils 1 day after ischemia and significantly decreased the neuronal death and glial activation in the hippocampal CA1 region 4 days after ischemia." (PMID 31957985, 2020). "Administration of Tat‐PDIA3 significantly reduced ischemia‐induced spontaneous motor activity, and the number of NeuN‐positive nuclei in the Tat‐PDIA3‐treated ischemic group was significantly increased in the CA1 region compared to that in the vehicle‐treated ischemic group." (PMID 31957985, 2020). "In addition, Tat‐PDIA3 significantly ameliorated ischemia‐induced changes of UPRs levels after ischemia/reperfusion." (PMID 31957985, 2020). "Indeed, PDIA3 (ERp57) protects from ischemia-induced brain damage." (PMID 33504070, 2021). "In the Tat‐PDIA3‐treated ischemic group, spontaneous motor activity was less increased compared to that in the vehicle‐treated ischemic group and the ratio of motor activity before and after ischemia was significantly decreased to 1.62 compared to that in the vehicle‐treated ischemic group." (PMID 31957985, 2020). "PDIA3 also potentially ameliorated the ischemia-induced increase in oxidative markers in serum and decreased the activity of Cu,Zn-superoxide dismutase, Mn-superoxide dismutase, and glutathione peroxidase in spinal cord homogenates, 24 h and 72 h after ischemia/reperfusion." (PMID 28981094, 2017). "Our data also suggest that PDIA3 plays a detrimental role under pathological conditions such as OGD, which mimics key aspects of ischemia." (PMID 34922569, 2021). "In the Tat-PDIA3-treated group, SOD1 activity also significantly increased (1.422-fold) 24 h after ischemia/reperfusion, which was maintained at 72 h after ischemia/reperfusion when SOD1 activity was significantly higher (1.579-fold) than the vehicle-treated group." (PMID 28981094, 2017). "In the Tat-PDIA3-treated group, SOD2 activity significantly increased (1.249- and 1.271-fold, respectively) compared with the vehicle-treated group 24 h and 72 h after ischemia/reperfusion, and to the control." (PMID 28981094, 2017).
lung carcinoma (6 papers, 2017 to 2025). "For example, FKBPL was associated with parental history of lung cancer, hip circumference, and vigorous physical activity levels, while PDIA3 was linked to parental history of lung cancer and body mass index." (PMID 41463415, 2025). "PDIA3 mutations have implications in lung cancer via abnormal immunosurveillance, while FOXP3 acts as a co‐activator in NSCLC, promoting Wnt/β‐catenin signaling, epithelial‐mesenchymal transition, and metastasis." (PMID 39945555, 2025). "Notably, parental history of lung cancer was the most significant mediator in the PDIA3-LUSC causal relationship, accounting for 69.46% of the effect and strongly associated with increased LUSC risk (OR = 2.67; 95% CI 1.73–4.11; p = 8.83 ×10−6)." (PMID 41463415, 2025).